MYCN (MYCN proto-oncogene, bHLH transcription factor)
Diseases named in the same sentence as MYCN in open-access papers (continued):
Sharing a sentence is not in itself a finding about the gene and the disease.
neuroblastoma (continued). "While this review focuses on pediatric brain tumors, MYCN also plays a crucial role in neuroblastoma, the most common extra-cranial solid tumor in childhood mainly arising in the adrenal medulla or sympathetic ganglia along the paraventral axis." (PMID 40365336, 2025). "It has previously been described those changes in the ATRX gene (Alpha Thalassemia/Mental Retardation, X-linked) are the most common recurring events in the indolent clinical subtype (∼30 %) of MYCN amplified neuroblastoma." (PMID 40286729, 2025). "This homeostasis seems disturbed in neuroblastoma, where MYCN upregulation coincides with the severely increased expression of certain miRNAs." (PMID 41142119, 2025). "ATP13A3 silencing also sensitized MYCN‐amplified (KELLY) and non‐MYCN‐amplified (SH‐SY5Y) neuroblastoma cells to escalating DFMO concentrations, which resulted in reduced growth and colony‐forming capabilities." (PMID 39981745, 2025). "Given the high degree of heterogeneity found within neuroblastomas with respect to MYCN genome copy number, a diverse cohort of neuroblastoma cell lines was selected for screening." (PMID 40456709, 2025). "The key prognostic factors include age ≥18 months, MYCN oncogene amplification, advanced International Neuroblastoma Staging System (INSS) stage (III/IV), and unfavorable histology." (PMID 40599792, 2025). "Most neuroblastomas amplify MYCN or delete miRNAs that bind to MYCN mRNA, suggesting that MYCN is a key driver." (PMID 39755235, 2025). "Here we established a kinetic model for the energy metabolism in neuroblastoma cell lines and analysed all described MYCN targets." (PMID 40993267, 2025). "We silenced SLC3A2 expression in non‐MYCN‐amplified (SH‐SY5Y) as well as MYCN‐amplified (KELLY) neuroblastoma cells and subsequently measured putrescine and spermidine uptake." (PMID 39981745, 2025). "NXT1 has been identified as a rapidly lethal factor in other diseases, such as MYCN-amplified neuroblastoma." (PMID 41578763, 2025). "Analogous to KIFC2, the proto-oncogene MYCN is amplified and promotes pyrimidine nucleotide biosynthesis in neuroblastoma cells." (PMID 40299549, 2025). "We further assessed the in vivo tumorigenicity of MYCN-amplified neuroblastoma cells transfected with shKLHL37." (PMID 40493396, 2025). "MYCN amplification primes neuroblastoma cells by upregulating pro-apoptotic BCL-2 family member NOXA, creating vulnerability for BCL-2 inhibition by venetoclax." (PMID 41034452, 2025). "Both SK4454 and SK5527 retained potentand selective AURKA degradation capacity, effectively reducing MYCNlevels in MYCN amplified neuroblastoma cells." (PMID 41252673, 2025). "Our findings support a role for ATP13A3‐mediated polyamine uptake in both MYCN‐amplified and non‐MYCN amplified neuroblastoma cells." (PMID 39981745, 2025). "ONC201 and ONC206 showed potent activity against the MYCN-amplified IMR-32 and non-MYCN-amplified SK-N-SH human neuroblastoma cell lines via a novel mechanism (inhibition of EGF-induced L1CAM and PDGFRb phosphorylation)." (PMID 41020897, 2025). "Amplification of the MYCN gene has been found in most malignant neuroblastomas, occurring in about 20% of the all cases." (PMID 41536427, 2025). "MYCN amplification in neuroblastoma induces structural changes in the mitochondrial network to adapt to altered energy demands." (PMID 41244073, 2025). "Taken together, RTA-408, functioning as an inhibitor of KLHL37, showed a promising therapeutic effect on MYCN-amplified neuroblastoma cells." (PMID 40493396, 2025). "The relative expression ratio of MAX to MYCN is a key factor in disease progression and clinical prognosis: a higher MAX/MYCN ratio can inhibit the oncogenic effects of MYCN and improve neuroblastoma prognosis." (PMID 41244073, 2025). "Chromosome 17q is amplified in the vast majority of neuroblastomas, and 11q, carrying a negative regulator of MYCN expression, is lost in about half." (PMID 39755235, 2025).
neuroblastoma (continued). "As anticipated, we observed that both Cas9D10A and Cas9H840A reduced cell viability when targeting LINE-1 or MYCN in MYCN-amplified neuroblastoma cell lines." (PMID 40456709, 2025). "MYCN is a well-known oncogene that is overexpressed in various malignant tumors, including neuroblastoma, rhabdomyosarcoma, medulloblastoma, and small-cell lung cancer." (PMID 40136455, 2025). "A tandem duplication model for HSR had previously been suggested for the MYCN amplification in the human neuroblastoma cell line IMR-5/7512." (PMID 41422275, 2025). "SR1078 can upregulate and activate RORα, restore the expression and activation of BMAL1, effectively block MYCN-mediated tumor growth, and enhance the sensitivity of neuroblastoma to chemotherapy." (PMID 41425709, 2025). "Advanced neuroblastoma, particularly the MYCN-amplified form, which exhibits highly aggressive properties, enhances glycolysis and relies on reduced glutathione (GSH) for ROS detoxification." (PMID 41291487, 2025). "High expression of MYCN, PRMT5 and E2F1 in neuroblastoma cells derived from high‐risk disease causes a deregulated alternative RNA splicing programme and resistance to cell death." (PMID 39021294, 2025). "Together, these results suggest that NIPBL sustains the undifferentiated state of MYCN-amplified neuroblastoma cells by maintaining MYCN expression and supporting the MYCN-driven repression of neuronal differentiation programs." (PMID 40867243, 2025). "There were three patients on this study with prolonged stable disease, including one patient with MYCN‐amplified neuroblastoma." (PMID 41308010, 2025). "Among the differentially expressed genes in the receptive endometrium, MYCN (v-myc myelocytomatosis viral-related oncogene, neuroblastoma-derived (avian)) was predicted as a target gene of the 5′-isoforms of miR-449c and let7g-5p." (PMID 41283360, 2025). "Reminiscent of ATP13A3 silencing, a sublethal dose of AMXT 1501 also sensitized MYCN‐amplified and non‐MYCN‐amplified neuroblastoma cells to DFMO in colony formation assays." (PMID 39981745, 2025). "Suppressing KLHL37 effectively induced the degradation of N-Myc and had a profound inhibitory effect on the growth of MYCN-amplified neuroblastoma." (PMID 40493396, 2025). "Inhibition of AurA by siRNA knockdown in a MYCN-amplified neuroblastoma cell line has shown to reduce MYCN protein levels and lower cell viability." (PMID 40365336, 2025). "This suggests they are primarily responsible for the eventual development of neuroblastoma tumors in Th-MYCN+/− mice." (PMID 40580553, 2025). "This approach not only destabilizes the MYCN protein but also compromises the DNA damage response mechanisms that neuroblastoma cells rely on to survive R-loop-induced genomic stress." (PMID 40629041, 2025). "Future studies should aim to further delineate how MYCN-driven glycosylation patterns interact with the immune microenvironment and explore the therapeutic potential of modulating glycosylation pathways in MYCN-amplified neuroblastoma." (PMID 39860532, 2025). "In MYCN-amplified LAN-1 neuroblastoma cells, induction of iHIF2α results in slowed cellular growth and reduced incorporation of 5-ethynyl-2′-deoxyuridine (EdU)." (PMID 41118218, 2025). "Proliferation-associated protein 2G4 (PA2G4) directly binds to and stabilizes MYCN protein, leading to markedly increased MYCN levels in neuroblastoma cells." (PMID 41002386, 2025).
neuroblastoma (continued). "Many sporadic neuroblastomas are driven by amplification of MYCN and segmental chromosomal alterations (including 1p and 11q loss of heterozygosity, and 17q gain)." (PMID 39847050, 2025). "CRC transcription factors bind with MYCN at cell-type-specific super-enhancers, forming an interconnected, self-reinforcing transcriptional network that governs the neuroblastoma-specific transcriptome." (PMID 40867243, 2025). "This heterogeneity underscores the complex biology of neuroblastoma and the differing responses to treatment, which are likely influenced by factors such as tumor genetics (e.g., MYCN amplification), prior treatment exposure, and patient age." (PMID 39941606, 2025). "TERT rearrangements are usually not accompanied by TERT CNVs, in contrast to high-level MYCN amplifications in aggressive neuroblastoma cell clones harboring MYCN breakpoints." (PMID 39760332, 2025). "MYCN is the pivotal neuroblastoma oncogene that is overexpressed in nearly all advanced cases of this neoplasm." (PMID 39714760, 2025). "Our study demonstrated the enrichment of the MYCN oncogene and clinically relevant glycolytic proteins in neuroblastoma cell-derived sEVs." (PMID 41440947, 2025). "The Th-MYCN mouse model, targeting human MYCN expression to the neural crest, recapitulates poorly differentiated late-stage neuroblastoma in an immunocompetent mouse." (PMID 40766251, 2025). "The tumor response was monitored by ultrasound imaging of MYCN/ALKF1178L mice that developed neuroblastoma in the abdomen." (PMID 40962798, 2025). "Recent studies have established that the marinopyrrole A derivative MP1 exerts direct mechanistic effects on the MYC family of oncogenes, particularly MYCN in neuroblastoma and MYC in medulloblastoma." (PMID 41149606, 2025). "The current International Neuroblastoma Risk Group (INRG) stratification system mainly relies on static indicators such as age, stage, and MYCN amplification, making it difficult to predict treatment responses in real time." (PMID 41267975, 2025). "MYCN has a short half-life of about 30 minutes, but in MYCN-amplified neuroblastoma cells, MYCN expression can be maintained at a high level." (PMID 40365336, 2025). "For example, in MYCN-amplified neuroblastoma cells, Aurora kinase A (AurA) can bind to MYCN and stabilize the protein." (PMID 40365336, 2025). "We present the first in vivo evidence demonstrating the essential role of PA2G4 in MYCN-driven neuroblastoma." (PMID 41002386, 2025). "We first confirmed that 1 mm of DFMO treatment significantly increased the uptake of radiolabeled putrescine and spermidine in both non‐MYCN amplified and MYCN‐amplified neuroblastoma cells." (PMID 39981745, 2025). "Targeting LARG with Y16 in neuroblastoma has been shown to promote differentiation, induce MYCN degradation, and reduce tumorigenicity, suggesting a translatable therapeutic approach for targeting LARG." (PMID 41338458, 2025). "MYCN gene amplification is more observed in neuroblastomas with higher INSS stages (Stages 3 and 4)." (PMID 40302936, 2025). "The functional roles of glycosyltransferase genes and their impact on tumor–immune interactions and tumor progression can be examined using patient-derived organoids or employing animal models, such as MYCN-driven neuroblastoma mouse models." (PMID 39860532, 2025). "Supporting this possibility, previous studies have shown that BRD4 inhibition reduces MYCN expression in neuroblastoma cells." (PMID 40867243, 2025). "In neuroblastoma and lymphoma, MYCN and MYC function as upstream regulators of PUS7, driving its expression and contributing to tumor progression." (PMID 40940790, 2025). "Cabozantinib exhibits activity against neuroblastomas arising in both Th-MYCN and Th-MYCN/ALKF1174L mice, revealed in situ using MRI." (PMID 40359728, 2025).
neuroblastoma (continued). "A preclinical study examined the synergistic effects of JQ1 (BRD4 inhibitor) and Alisertib (AURKA inhibitor) in MYCN-amplified neuroblastoma cell lines and mouse models." (PMID 40365336, 2025). "The oncogenic driver neuroblastoma-derived MYC (MYCN) exacerbates ER stress by increasing calcium ion efflux from the ER into mitochondria, promoting glycolytic and oxidative stress." (PMID 41198652, 2025). "At relapse, bone marrow DTCs reached 1.59%, but tumor cells were negative for GD2 and the fraction of CD56-expressing cells was lower, while all tumor cells carried the neuroblastoma-typical MYCN oncogene amplification." (PMID 40753395, 2025). "Our findings demonstrate the pivotal role of MYCN amplification in neuroblastoma, shaping both gene expression profiles and the immune landscape in ways that directly correlate with clinical outcomes." (PMID 39860532, 2025). "To investigate the functional importance of PA2G4 in MYCN-driven neuroblastoma in vivo, we utilized the Th-MYCN transgenic mouse model, in which the human MYCN gene is expressed under the control of the tyrosine hydroxylase promoter." (PMID 41002386, 2025). "For example, multidrug resistance-associated protein 1, a member of the ABC family of transporters, is known to be associated with drug resistance and has been identified as a downstream transcriptional target of MYCN in neuroblastoma." (PMID 39802403, 2025). "In neuroblastoma, MYCN-induced E2F5 enhances cell proliferation by regulating cell cycle progression." (PMID 40862719, 2025). "Our findings have revealed a promising strategy to treat MYCN-amplified neuroblastoma by inhibiting KLHL37." (PMID 40493396, 2025). "Together, these results suggest that NIPBL maintains the MYCN-driven transcriptional program that promotes cell proliferation and a stem-like identity in neuroblastoma cells." (PMID 40867243, 2025). "We used GSK983, a small molecule degrader optimized for drug-like properties, to target the transcriptional coactivator KAT2A in MYCN-driven neuroblastoma." (PMID 40274766, 2025). "By analyzing GSE85047 cohort, we found that KLHL37 was significantly upregulated in patients with MYCN-amplified neuroblastoma." (PMID 40493396, 2025). "In this study, we have revealed that KLHL37 was aberrantly overexpressed in neuroblastoma cells and closely related with a poor prognosis for patients with neuroblastoma, especially those harboring MYCN gene amplification." (PMID 40493396, 2025). "Transgenic mice with tyrosine hydroxylase promoter-driven expression of MYCN in the neural crest developed neuroblastoma, indicating that MYCN amplification alone is sufficient to induce the development of this cancer." (PMID 39802403, 2025). "It has been shown that most malignant neuroblastomas have the amplification of MYCN, which is found in approximately 20% of tumors." (PMID 41142119, 2025). "Evidence highlights MYCN’s role in neuroblastoma, where it modulates cell proliferation and apoptosis through its interaction with the transcriptional target NLRR1." (PMID 40593489, 2025). "BCT-100 efficacy was assessed in the Th-MYCN transgenic neuroblastoma mouse model and in neuroblastoma cell line and patient-derived xenograft models." (PMID 40813699, 2025). "Downstream mechanistic pathways diverge, manifesting as metabolic and mitochondrial collapse in MYCN-amplified neuroblastoma, whereas transcriptional and translational repression predominates in MYC family-driven medulloblastoma." (PMID 41149606, 2025). "Our findings provided a set of miRNAs that have the potential to the post-transcriptional regulation of MYCN in neuroblastoma and indicated new targets for MYCN oncogene inhibition." (PMID 41142119, 2025).
neuroblastoma (continued). "Analysis of 556 published neuroblastoma genome-wide copy-number profiles identified 238 neuroblastomas with MYCN amplifications." (PMID 38197697, 2024). "Here, the authors identify that the transcriptional corepressor Runx1t1 is indispensable for MYCN-driven neuroblastoma tumorigenesis." (PMID 38992040, 2024). "Specifically, Bao and colleagues identified T-cell signatures that were predictive of outcome in neuroblastoma patients in a MYCN-independent fashion." (PMID 39099200, 2024). "GD2 expression was shown to be elevated in oral malignant osteosarcoma samples and neuroblastoma with MYCN amplification, which also negatively affects the forecast." (PMID 38558810, 2024). "As MYCN amplification has been shown to increase RS it is considered as a possible additional biomarker for use of CHK1i like prexasertib in neuroblastoma." (PMID 38279263, 2024). "Another illustrative example comes from studies of neuroblastomas, in which MYCN amplification plays a critical role in disease progression." (PMID 38428031, 2024). "Because of the fundamental role played by N-Myc in neuroblastoma, we examined the impact of AF1q silencing on N-Myc in (MYCN amplified) Kelly and Lan-5 cells and on C-Myc in (MYCN non-amplified) SH-SY5Y cells." (PMID 38413795, 2024). "Another case involves NCYM (or MYCNOS), the anti-sense gene of MYCN, serving a specific function of inhibiting GSK3β and stabilizing MYCN in human neuroblastomas." (PMID 39088850, 2024). "It is still unclear if and how oncogenic MYCN or specific features of the cell of origin trigger ferroptosis sensitivity of neuroblastoma cells." (PMID 38908072, 2024). "MYCN upregulates proliferation and apoptosis that target the Wnt/β-catenin signaling pathway, and hence acts as the major factor in the development of neuroblastoma." (PMID 38929279, 2024). "We next sought to interrogate where in the genome the SAGA complex is recruited in MYCN-amplified neuroblastoma, using TADA2B as a proxy for the SAGA complex." (PMID 38820154, 2024). "While the Th-MYCN model is considered the standard for the preclinical study of MYCN-amplified neuroblastoma, manual palpation is used to determine tumor burden." (PMID 39668192, 2024). "The adrenergic II pre-neuronal-like program was also observed in multiple other datasets and the “neuroblastoma-MYC” (high-risk) program formed a dense hub, with similar programs recovered in high-risk (both MYC and MYCN overexpressing) tumors in all datasets." (PMID 38898465, 2024). "Clinical behavior of bilateral suprarenal neuroblastoma is exceptional with several multicystic forms, variable MYCN amplification, widespread metastases and high mortality." (PMID 38607453, 2024). "SESN1 is a downstream target of MYCN and functions as a new tumor suppressor gene via Toll‐like receptor signaling pathway in neuroblastoma." (PMID 38516781, 2024). "The Th-MYCN neuroblastoma mouse model, involving targeted expression of human MYCN to neural crest cells, recapitulates aggressive human neuroblastoma." (PMID 38992040, 2024). "Analysing our dataset offers valuable insights into TrkA/B/C receptor signalling in neuroblastoma and its modulation by MYCN status; and holds potential for advancing therapeutic strategies in this challenging childhood cancer." (PMID 39389992, 2024). "UNC0642, a more potent analog of UNC0638 with better in vivo pharmacokinetics, inhibited growth in several pediatric cancers, including MYCN-amplified neuroblastoma, Ewing sarcoma, and ARMS." (PMID 39766049, 2024). "The METTL3 small molecule inhibitor STM2457 targets m6A modification, down‐regulates MYCN expression and inhibits tumour proliferation, providing a new therapeutic strategy for MYCN‐amplified neuroblastoma." (PMID 39135292, 2024). "We report a role for the SAGA complex acetyltransferase activity in maintaining the oncogenic state in MYCN-amplified neuroblastoma, expanding the universe of histone-modifying complexes that are central to maintaining the disease state." (PMID 38820154, 2024).